TF (transferrin)
Diseases named in the same sentence as TF in open-access papers (continued):
Sharing a sentence is not in itself a finding about the gene and the disease.
iron deficiency (continued). "Therefore, we suggest that ABI/VP1 TF gene identified in our research could play an indirect role in salinity tolerance via activating IDE-type genes which in turn transactivates the Fe deficiency-induced gene(s) to overcome iron deficiency by absorption higher amounts of Fe under salt stress." (PMID 33420909, 2021). "Signs of iron deficiency were present in around 20% of patients: 18.5% had a ferritin of <30 μg/L and 24.2% had a transferrin saturation (TSAT) lower than 20% without overt anemia in this cohort." (PMID 34575218, 2021). "As the iron deficiency worsens, transferrin saturation decreases as not enough iron can be mobilized to meet demands." (PMID 34575361, 2021). "Iron deficiency non-anemia has been commonly defined in athletic populations as a serum ferritin of <20 μg·L−1 and transferrin <16%; however, variations in the literature range from serum ferritin values of <12 μg·L−1 through to <40 μg·L−1." (PMID 33265953, 2020). "Fourthly, anemia status in this study was only based on hemoglobin levels, and we did not consider iron deficiency anemia because a large number of participants had missing data in transferrin saturation and total iron binding capacity." (PMID 31480674, 2019). "Because anemia is the best recognized indicator of iron deficiency, the diagnosis of iron deficiency in the context of PV, and thus without anemia, requires the identification of ferritin, transferrin saturation, and MCV below the lower limit of normal." (PMID 30042411, 2018). "The standard threshold for iron deficiency (<30 μg/L) therefore does not apply and transferrin saturation (TSAT), a marker of iron availability, should also be assessed." (PMID 29744352, 2018). "As we did not obtain the data on serum iron, serum ferritin and serum transferrin saturation, etc, we cannot calculate the prevalence of iron deficiency anaemia in our study." (PMID 29044219, 2017). "In 409 patients with iron deficiency, in addition to transferrin saturation, ferritin was also available at the same time, 335 patients (81.9%) had functional iron deficiency (20%> TSAT, 30 ng/ml≤ Ferritin) and 74 (18.1%) had absolute iron deficiency." (PMID 28989585, 2017). "Given that transferrin is the major iron transporter protein, one would anticipate increased rather than decreased transferrin saturation in mild iron deficiency." (PMID 28221362, 2017). "Changes in the prevalence of iron deficiency as measured by serum ferritin, serum transferrin, and body iron stores, from baseline to endpoint were not significant between and within groups during the study." (PMID 28895887, 2017). "As iron crosses the blood–brain barrier bound to transferrin, the correlation between peripheral transferrin saturation and low iron levels in the red nucleus in CUD patients also concurs with the notion of peripheral iron deficiency." (PMID 28221362, 2017). "In the present study, transferrin levels have not been measured and the contribution of iron deficiency to the observed stimulation of eryptosis thus remains uncertain." (PMID 26872376, 2016). "Complete iron profile including transferrin, rather than serum ferritin alone, can truly predict iron deficiency in such people." (PMID 28116148, 2016). "However, some of the laboratory findings indicating iron deficiency (low MCV, mean corpuscular Hb [MCH], serum iron, and transferrin saturation) had persisted." (PMID 25805669, 2015). "Instead, in the present study, we have used percentage saturation of transferrin, the value of which does not overlap with the normal values and the values less than 16% occur in iron deficiency and anaemia of chronic diseases." (PMID 25400943, 2014). "The proportion of SCA children with low transferrin saturation (<16%) indicating probable iron deficiency, was 28% (126/458) but was lower than that in non-SCA Tanzanian control children (32/62, 52%)." (PMID 23691341, 2013).
iron deficiency (continued). "Most patients had a non anaemic haemoglobin level (Hb ≥11 g/dL: 66%) with no iron deficiency [ferritin level ≥100 ng/mL: 59%; transferrin saturation (TSAT) ≥20%: 63%]." (PMID 23659341, 2013). "Iron deficiency in nonpregnant populations can be measured quite precisely using laboratory tests such as serum ferritin, serum iron, transferrin, transferrin saturation, and transferrin receptors." (PMID 22848829, 2012). "In absolute iron deficiency, i.v. administrated iron-carbohydrates rapidly enter RES macrophages, where they are processed, thus releasing iron from these cells and delivering it to erythroblasts by transferrin." (PMID 22111015, 2011). "Any other traditional compound indices of iron-deficiency, e.g. by accounting for mean cell volume, mean corpuscular haemoglobin, and transferrin saturation did not identify any additional cases of clinical overt iron deficiency." (PMID 16000177, 2005). "While iron deficiency is presumed to be the predominant cause, the lack of confirmatory tests (e.g., ferritin, transferrin saturation) limits our ability to differentiate it from other forms such as B12 or folate deficiency, anemia of chronic disease, or hemoglobinopathies." (PMID 40725741, 2025). "Alongside ferritin and transferrin saturation (TSAT), various additional laboratory markers may aid in diagnosing iron deficiency in heart failure (HF), especially in intricate cases where inflammation, renal impairment, or other comorbidities complicate the interpretation of standard metrics." (PMID 40363966, 2025). "Because plasma iron alone may not diagnose iron deficiency, iron status should be assessed with a panel including transferrin saturation and ferritin." (PMID 41306959, 2025). "Notably, patients with higher inflammatory activation had lower serum iron and transferrin saturation and higher sTfR, consistent with early functional iron deficiency, though ferritin and hepcidin were not significantly different between groups." (PMID 41374035, 2025). "Absolute iron deficiency is due to the severe reduction in iron stores in the liver and reticular-endothelial system and is commonly diagnosed by a reduction in serum ferritin with or without low transferrin saturation." (PMID 38732502, 2024). "The National Comprehensive Cancer Network (NCCN) guidelines classify CIA into four groups (absolute iron deficiency, functional iron deficiency, possible functional iron deficiency, and no iron deficiency) based on transferrin saturation (TSAT) and ferritin values." (PMID 39712704, 2024). "In most cases with iron disorders, especially in cases with overweight and obesity, ferritin was considered as a marker of inflammation rather than iron status and other related markers; transferrin, iron concentrations, sTfR, and Hgb alone can truly predict iron deficiency in such people." (PMID 38102707, 2023). "The most frequently used definition of iron deficiency (ID) in patients with cardiovascular disease is ferritin < 100 μg/L or ferritin 100–299 μg/L and transferrin saturation (TSAT) < 20%, however recent studies suggested that relying on ferritin for diagnosis of iron deficiency may be suboptimal." (PMID 36975880, 2023). "Furthermore, serum transferrin saturation (serum iron/total iron‐binding capacity [TIBC] ×100%) was lower in AMPKα1–/– mice than in WT and AMPKα2–/– mice, reflecting the presence of iron deficiency in AMPKα1–/– mice." (PMID 35538889, 2022). "However, international guidelines define the iron deficiency condition as when serum ferritin values are <100 μg/L, either related or not to a transferrin saturation <20% and suggest that attention should be paid to the condition of iron depletion." (PMID 36499124, 2022). "Moreover, studies have shown that iron deficiency is associated with elevated number of platelets as it was determined by a negative correlation between platelet count and transferrin saturation in CKD patients." (PMID 35813388, 2022).
iron deficiency (continued). "A recent study evaluating prevalence of iron deficiency in the first trimester among non-anemic pregnancy women found that using standard cutoffs of percent transferrin saturation and/or serum ferritin, 42% of non-anemic women in their first trimester were iron deficient." (PMID 33804474, 2021). "Because most female patients enrolled in our study were beyond the age of menopause and transferrin saturations were similar between the BCL subclasses, the sex difference in blood cadmium in CKD patients might be attributed to causes other than iron deficiency or menstrual blood loss." (PMID 34886064, 2021). "However, if functional iron deficiency results of supply/demand mismatch, for example, during treatment with ESA, iron may transfer from transferrin faster than it can be mobilized from the iron stores, resulted in TSAT decrease." (PMID 33025407, 2021). "However, the possibility of an iron deficiency anemia was not investigated in our study as the possible presence of fecal occult blood, as well as the iron profile (serum iron, ferritin, and transferrin), were not included." (PMID 34573547, 2021). "Therefore, the standard threshold for iron deficiency does not apply and transferrin saturation (TSAT), a more sensitive marker of iron availability, should also be assessed if possible." (PMID 31971986, 2020). "Thus, Iron deficiency shifted the microbial structure towards bacterial species more resistant to iron starvation conditions and/or those more capable of utilizing transferrin and lactoferrin rather than haem and haemoglobin." (PMID 31752810, 2019). "Within our study, and even despite significantly fewer patients transfused, at 1 month post-surgery, as overall, the FCM-treated patients did not reflect signs of anemia, as well as no signs of iron deficiency (mean ferritin and transferrin saturation index were at normal values)." (PMID 26694926, 2016). "In the final phase (iron deficiency anemia), oxygen supply to tissues is impaired, which is reflected by a decrease in hemoglobin concentrations, hematocrit, mean corpuscular volume (MCV), mean corpuscular hemoglobin (MCH), serum ferritin, serum iron, and transferrin saturation." (PMID 25849944, 2015). "Serum TF protein still remains about 70% of normal as revealed by Western blot data, suggesting that the symptoms in Hnf4aΔH mice would not be severe enough to develop iron deficiency anemia." (PMID 26527688, 2015). "In addition, her serum ferritin concentration (62 ng/mL, reference of 12–60 ng/mL) was not low, it was slightly high, while her serum transferrin concentration (174 mg/dL, reference of 190–320 mg/dL) was low, not elevated, indicating that anemia was not derived from an iron deficiency." (PMID 39111871, 2024). "Moreover, the ferritin level and transferrin saturation values indicate a human’s different iron status; yet, we cannot say whether iron deficiency was supported by the ferritin level or transferrin saturation due to the lack of serum iron indicators." (PMID 35267982, 2022). "However, analysis of parameters related to iron deficiency, such as the hematocrit level and erythrocyte count, was lacking in this study; similarly, indicators of iron status, including serum iron level, transferrin saturation, and ferritin, were not measured." (PMID 35631204, 2022). "Taken together, these data suggested that iron deficiency might not directly increase the pathological changes in autism, and might contribute to a higher risk of autism indirectly via elevating the expression of transferrin." (PMID 36407516, 2022). "Due to increased red cell turnover and hemodilution, which makes determining iron deficiency anemia less reliable, more sensitive methods such as serum iron, total iron-binding capacity and transferrin could have been measured, but we did not have the capacity to measure these parameters." (PMID 32183478, 2020).
iron deficiency (continued). "First, the combination of high serum iron, TF-Sat and ferritin may primarily be attributable to immune-driven alterations of iron metabolism whereas suppressed hepcidin is a clear although not well-standardized indicator of absolute iron deficiency." (PMID 33014378, 2020). "Furthermore, changes in serum levels of traditional iron parameters such as iron, transferrin saturation, and ferritin may not always correlate with the functional iron deficiency (FID) status of the patient." (PMID 30281654, 2018). "In addition, transferrin saturation calculated as the iron/TIBC ratio may not be a perfect marker of iron deficiency due to the contribution from a certain portion of non-transferrin bound iron." (PMID 30412998, 2018). "On the other hand, iron deficiency anemia (IDA) is defined by low serum ferritin (<30 ng/mL without inflammation and <100 ng/mL with inflammation) and low transferrin saturation (<20%) in addition to low Hb levels (<13.5 g/dL for men and <12 g/dL for women)." (PMID 38068803, 2023). "In patients without severe iron deficiency and with normal CRP levels, hepcidin-25 was correlated with ferritin, and inversely correlated with TF and mean corpuscular volume (MCV) values." (PMID 23433094, 2013). "Furthermore, Klotho administration did not improve iron deficiency in CKD mice but it decreased intestinal absorption of iron in control mice leading to reduced serum iron and transferrin saturation levels." (PMID 35813388, 2022).
anemia (477 papers, 2003 to 2026). A reduction in the number of red blood cells, the amount of hemoglobin, and/or the volume of packed red blood cells. "Elevated BM iron was significantly associated with more severe anaemia, higher SF levels, and lower transferrin levels." (PMID 42271097, 2026). "Multivariate logistic modeling confirmed that low serum zinc independently predicted anemia risk, alongside transferrin saturation and C- reactive protein levels." (PMID 41599845, 2026). "The only associations noted were between malnutrition and transferrin levels with postoperative length of stay, observed only in bivariate analysis, likely due to confounding factors like age and anemia." (PMID 40727701, 2025). "Given that iron-deficiency anemia is a common cause of anemia in cancer patients, it is essential not only to assess hemoglobin levels but also to evaluate serum ferritin and transferrin saturation." (PMID 40322886, 2025). "Decreased ferritin level is usually the first indicator of depleted iron stores, and reduced transferrin saturation and anemia appear only at later stages of iron deficiency." (PMID 41470772, 2025). "Further workup revealed iron deficiency anemia with transferrin saturation of 11%, which was managed with oral iron supplementation of polysaccharide iron complex 150 mg once daily." (PMID 39221385, 2024). "Nephrotic syndrome, characterized by oedema, hypoalbuminaemia, dyslipidaemia, and increased transferrin catabolism, contributes to anaemia due to iron and erythropoietin deficiency." (PMID 38562414, 2024). "Untreated CD cases suffer from iron deficiency anemia (IDA) which results in higher peaks of transferrin, reflecting upsurge in protein translation." (PMID 36778054, 2023). "Mutations in the gene encoding transferrin (MIM #209300) cause a very rare recessive autosomal anemia due to reduced iron delivery to the bone marrow and severe iron overload." (PMID 36986429, 2023). "Anemia of inflammation most often presents as normocytic, normochromic anemia linked to decreased transferrin saturation (<20%) but increased serum ferritin levels." (PMID 37361544, 2023). "Transferrin plays a vital role in transporting iron to erythroid precursors in the bone marrow, maturity dysfunction of which would cause anemia." (PMID 36407516, 2022). "In pediatric patients with anemia caused by other factors, including anemia of inflammation, values were higher than the normal range, as expected due to the inflammatory decrease in transferrin, which increased TSAT." (PMID 34441801, 2021). "Specifically, 26.5% of respondents misdiagnosed a scenario of IDA as anemia with an alternate cause despite a low transferrin saturation (2%) and a borderline low ferritin level (40 ng/mL)." (PMID 34596670, 2021). "Previous studies have found that the TCM Yi Gong San (YGS) can reduce the expression of transferrin by inhibiting hepcidin overexpression caused by inflammation, promote the outward transfer of intracellular iron, and improve the symptoms of anemia." (PMID 34663434, 2021). "Anemia is a frequently observed complication of nephrotic syndrome but occurs as a result of urinary loss of erythrogenic factors such as iron, transferrin and erythropoietin." (PMID 34203913, 2021). "This study uncovers pre-existing anemia as well as low transferrin concentrations as risk factors for mortality in hospitalized COVID-19 patients, whereas new-onset anemia during hospitalization is a risk factor for ICU admission." (PMID 34677368, 2021). "These neurologically asymptomatic patients were diagnosed following the onset of diabetes and/or anemia, during the diagnostic workup of unexplained hyperferritinemia with low transferrin saturation, or by family counselling." (PMID 32334607, 2020). "As an index of nutritional status, transferrin is limited and susceptible to dramatic changes following infection, decreased liver and kidney function, and anemia." (PMID 32382262, 2020).